PHAF1 (phagophore assembly factor 1)
Description:
Plays a regulatory role in autophagic activity. In complex with BCAS3, associates with the autophagosome formation site during both non-selective and selective autophagy.
Synonyms: C16orf6; C16orf70; lin-10; FLJ12076; MYTHO; LIN10
Tractability: PROTAC: ubiquitination databases record sites on it.
Gene: Protein-coding gene on chromosome 16 (67,109,941 to 67,148,544, forward strand). Ensembl gene ENSG00000125149.
Subcellular location: Cytoplasm; Preautophagosomal structure
Subcellular location (Human Protein Atlas): Nuclear speckles; Cytosol; Nucleoli fibrillar center
Gene Ontology:
Molecular function: protein binding
Biological process: Golgi to plasma membrane protein transport
Cellular component: cytoplasm; phagophore assembly site; dendrite; synaptic vesicle membrane; trans-Golgi network
Genetic constraint (gnomAD): Loss-of-function variants: 22 observed, 52.72 expected, observed/expected ratio (o/e) 0.42, 90% interval 0.3 to 0.6. The upper end of that interval is the gene's LOEUF score, 0.6, which puts it in group 2 of 6, group 1 being the genes least tolerant of losing a copy. Missense variants: 387 observed, 467.27 expected, observed/expected ratio (o/e) 0.83, 90% interval 0.76 to 0.9. Synonymous variants: 150 observed, 171.25 expected, observed/expected ratio (o/e) 0.88, 90% interval 0.77 to 1.
Homologues: Orthologues: chimpanzee PHAF1 (100% identical), macaque PHAF1 (99% identical), rabbit PHAF1 (99% identical), rat Phaf1 (98% identical), guinea pig PHAF1 (98% identical), pig PHAF1 (98% identical), mouse Phaf1 (97% identical), dog PHAF1 (88% identical), zebrafish phaf1 (88% identical), tropical clawed frog phaf1 (85% identical), Drosophila melanogaster CG7083 (54% identical). Paralogues in human: TBC1D32 (23% identical).
Diseases named in the same sentence as PHAF1 in open-access papers:
PHAF1 is named in the same sentence as 13 diseases in open-access papers, as found by Europe PMC text mining. Sharing a sentence is not in itself a finding about the gene and the disease.
PHAF1 shares sentences with these, for which no sentence is quoted: cancer (2 papers); myopathies (2); schizophrenia (2); Sepsis (2); acute myeloid leukemia (1); Atrophy (1); breast tumors (1); lung squamous cell carcinoma (1); muscle disorders (1); muscular dystrophies (1); myotonic dystrophy type 1 (1); neuromuscular genetic disease (1); tumor (1).